PVT1 (Pvt1 oncogene)
Diseases named in the same sentence as PVT1 in open-access papers (continued):
Sharing a sentence is not in itself a finding about the gene and the disease.
ovarian carcinoma (continued). "We found a strong correlation between an inactive Hippo gene signature (where YAP1 target gene signatures are expressed), and PVT1 expression in TCGA ovarian cancer datasets." (PMID 35820706, 2022). "PVT1 is a YAP1 dependent stress responsive lncRNA that promotes ovarian cancer metastasis and chemoresistance, making PVT1 a promising therapeutic target." (PMID 35820706, 2022). "Upregulation of lncRNA PVT1 increased cisplatin resistance via targeting apoptotic pathway in ovarian cancer." (PMID 36105363, 2022). "Together, these findings implicate PVT1 as a promising therapeutic target to suppress metastasis and chemoresistance in ovarian cancer." (PMID 35820706, 2022). "Reduced circular PVT1 lowered resistance to drug, revealing circular PVT1-mediated influence on ovarian cancer and the possibility of participating in drug resistance of ovarian cancer." (PMID 33391456, 2021). "Here, our findings identified the function and mechanism of circPVT1 and FOXM1 involved in ovarian cancer, indicating circular PVT1-mediated regulation of cell apoptosis and metastasis by way of targeting miR-149-5p axis." (PMID 33391456, 2021). "Our results implied that miR-149-5p was modulated by circular PVT1, thus inhibiting viability and apoptosis of ovarian cancer." (PMID 33391456, 2021). "Our data suggest that PVT1 promotes ovarian cancer metastasis through PVT1/miR‐148a‐3p/AGO1/TGF‐β axis." (PMID 34288373, 2021). "Kaplan‐Meier survival analysis showed that ovarian cancer patients with high PVT1 expression had a poor overall survival than patients with low PVT1 expression." (PMID 34288373, 2021). "Here, we selected the lncRNA PVT1, which is abundantly expressed in ovarian cancer, as a therapy target for ovarian cancer." (PMID 34288373, 2021). "Overall, these findings reveal that the expression of AGO1 was modulated through PVT1/miR‐148a‐3p axis in ovarian cancer." (PMID 34288373, 2021). "LncRNA-plasmacytoma variant translocation I (PVT1), metastasis-associated lung adenocarcinoma transcript 1 (MALAT1), and LINC00319 were demonstrated to be involved in ovarian cancer cell proliferation, migration, and invasion by acting as a ceRNA." (PMID 34900667, 2021). "In conclusion, our findings provide insight into PVT1/miR‐148a‐3p/AGO1 axis to be a novel therapy target for human ovarian cancer." (PMID 34288373, 2021). "To explore the role of PVT1 in ovarian cancer progression, we first determined the PVT1 expression in human tissues by RT‐qPCR, and the results showed that a higher expression of PVT1 was detected in ovarian cancer tissues compared to non‐tumour tissues." (PMID 34288373, 2021). "In this study, we found PVT1 RNA was an ovarian specific expressing gene, and overexpressed in multiple cancer types, including ovarian cancer (OV)." (PMID 33391456, 2021). "Taken together, the present study reveals that PVT1/miR‐148a/AGO1 axis plays an important role in the progression of ovarian cancer and emphasize the potential as a target of value for ovarian cancer therapy." (PMID 34288373, 2021). "Increased PVT1 expression was also observed in ovarian cancer patients with advanced FIGO stage and lymph‐node metastasis." (PMID 34288373, 2021). "The high expression of PVT1 in ovarian cancer cells promotes the proliferation, migration, and invasion ability of ovarian cancer cells." (PMID 31309249, 2019). "Similar results with higher variances (possibly due to the smaller size of the datasets) can be observed for EGFR amplifications in glioblastoma and LUSC, for PVT1 amplifications in ovarian cancer and for PTEN deletions in sarcoma." (PMID 31379928, 2019). "Accumulating evidence revealed that PVT1 was unregulated and played vital regulatory roles in a variety of cancers, including colorectal, pancreatic, breast and ovarian cancer." (PMID 30083911, 2019).
ovarian carcinoma (continued). "The expression of PVT1 in ovarian cancer tissues is higher than that in normal ovarian tissue and is related to the advanced stage of ovarian cancer and lower overall survival." (PMID 31309249, 2019). "Interfering PVT1 expression inhibited proliferation and induced apoptosis in breast and ovarian cancer cell lines." (PMID 29108264, 2017). "PVT1 is a 2430-nt-long lncRNA located in the 8q24 chromosomal region and neighboring myc, which is amplified in about half of ovarian carcinomas." (PMID 28637507, 2017). "Small interfering RNA–mediated reduction in either PVT1 or MYC expression can inhibit cellular proliferation of ovarian cancer." (PMID 28430593, 2017). "Conversely, over-expression of PVT1 contribute to the development of cisplatin resistance by regulating apoptotic pathways in ovarian cancer cells." (PMID 29108264, 2017). "Previous studies showed that PVT1 expression was increased in the tissues of cisplatin-resistant gastric and ovarian cancer patients, as well as in cisplatin-resistant cancer cells." (PMID 29108264, 2017). "More than 45% of 500 ovarian cancers from TCGA were shown to have amplification of both pvt1 and myc." (PMID 28637507, 2017). "Overexpression of PVT1 has been demonstrated in in a variety of cancer types including ovarian cancer." (PMID 28430593, 2017). "Recently, plasmacytoma variant translocation 1 (PVT1), a novel lncRNA, has been reported to be up-regulated in human cancers such as HCC, ovarian cancer and non-small lung cancer." (PMID 27588491, 2016). "In more than 1 000 ovarian cancers from TCGA, more than 45% displayed both pvt1 and myc amplification, with only a few cases (<1%) having only myc or pvt1 duplicated." (PMID 26992233, 2016). "Examples include some well-known lncRNAs, some of which are involved in ovarian cancer biology such as PVT1 and H19." (PMID 26992233, 2016). "This underlines the need for further studies on the exact role of the myc/pvt1 couple in ovarian cancer." (PMID 26992233, 2016). "While overexpression of PVT1 transcript has been documented in a variety of tumor tissues including breast and ovarian cancer and also in Hodgkin lymphoma, miR-1206 expression has been found in increased levels in B cell tumors such as Namalwa and CA-46." (PMID 23077621, 2012). "Surprisingly, on 8q24 both the GISTIC and frequency peaks were located ∼500 kb distally to the two previously implicated oncogenes in ovarian cancer within this locus, MYC and PVT1." (PMID 20844748, 2010). "This study provides more evidence on the regulation of PVT1 by m6A modification, which may aid in the development of effective therapeutic strategies for ovarian cancer." (PMID 38098223, 2024). "Therefore, it is necessary to further clarify the effect and mechanism of lncRNA PVT1 on ovarian cancer in many samples and a variety of ovarian cancer cell lines." (PMID 38098223, 2024). "However, in breast and ovarian cancers, PVT1 acts independently of MYC, acting as an anti-apoptotic protein." (PMID 36624401, 2023). "According to research, overexpression of PVT1 promotes malignant behavior in ovarian cancer cells, while downregulation of PVT1 inhibits it, suggesting that PVT1 may play an important role in cancer progression." (PMID 37573419, 2023). "Intriguingly, PVT1 may also serve as a good prognostic indicator for the early stages of some cancers, such as ovarian carcinoma." (PMID 37263709, 2023). "Ovarian cancer cells are affected by PVT1 through miR-370 sponges." (PMID 37573419, 2023). "Hence, to evaluate the clinical significance of PVT1 expression changes alone, we conducted Kaplan–Meier survival analysis using KM plotter in TCGA datasets that included all ovarian cancer patients with a best cutoff analysis." (PMID 35820706, 2022).
ovarian carcinoma (continued). "We first evaluated PVT1 expression at baseline using primers spanning PVT1 transcript isoforms containing–exon 1–2, exon 2–3, and exon 6–7 in a panel of human ovarian cancer (OVCA) cells lines, normal immortalized fallopian tube epithelial cells (p211) and surface epithelial cells (IOSE80)." (PMID 35820706, 2022). "This suggests that PVT1 has predictive value for survival and may play an important role in ovarian cancer and treatment outcomes." (PMID 35820706, 2022). "Bioinformatic analysis of TCGA datasets confirmed that chromosome 8q24.21 exhibits the highest copy number amplifications and that copy number alteration (CNA) frequency of PVT1 is among the highest in ovarian cancer, highlighting the significance and relevance of PVT1 to this cancer." (PMID 35820706, 2022). "However, the effects of AGO1 on ovarian cancer, and the relationship between PVT1 and AGO1 are currently unclear and therefore need to be explored." (PMID 34288373, 2021). "We next determined the effects of PVT1/miR‐148a‐3p/AGO1 axis on the ovarian cancer cell functions." (PMID 34288373, 2021). "In addition, functional inhibition of the PVT1 gene reduced proliferation in ovarian cancer cell lines." (PMID 34288373, 2021). "Our study revealed that circular PVT1 promoted the tumor progression in ovarian cancer." (PMID 33391456, 2021). "In ovarian cancer, two studies reported on the relevance of PVT1 in tumorigenesis." (PMID 34204094, 2021). "To deeply investigate the phenomenon of ovarian cancer cell viability and apoptosis induced by circular PVT1, we conducted bioinformatics analysis and found circular PVT1 regulated miR-149-5p in the form of ceRNA, and miR-149-5p directly bond to 3'UTR of FOXM1 mRNA to repress FOXM1 expression." (PMID 33391456, 2021). "Resistance to cisplatin by PVT1 overexpression has been reported in gastric and ovarian cancers." (PMID 30524948, 2018). "Increased expression of PVT1 in ovarian cancer cells may promote cisplatin resistance by regulating apoptotic pathways." (PMID 28430593, 2017). "In addition, several earlier findings implicate PVT1 in the pathophysiology of cancer, and silencing PVT1 expression using siRNA reduces cell proliferation and increases apoptosis in breast and ovarian cancer cell lines." (PMID 26305674, 2015). "Compared with healthy tissues, PVT1-lncRNA is overexpressed in breast and ovarian cancer, indicating that PVT1 may be an oncogene." (PMID 25663854, 2015). "This prompted us to confirm whether ALKBH5 regulates FOXM1 via PVT1 RNA in ovarian cancer." (PMID 38098223, 2024). "Given the significant amplification of PVT1 in ovarian cancer and the apparent clinical impact of increased expression of PVT1, we examined the effect of stressors, which may pertain to the metastatic trajectory of ovarian cancers and by altering PVT1 expression in different cell lines." (PMID 35820706, 2022). "However, the potential effects and mechanisms of PVT1 in carcinogenesis of ovarian cancer remain unknown." (PMID 34288373, 2021). "Furthermore, increased expression of PVT1 and its negative function in apoptosis caused cisplatin or carboplatin-docetaxel resistance in ovarian cancer." (PMID 29921308, 2018). "In conclusion, we demonstrate that ALKBH5 promotes tumour progression by at least partially stabilizing PVT1 and FOXM1 in ovarian cancer." (PMID 38098223, 2024). "LncRNA PVT1 is highly expressed in epithelial ovarian cancer tissues, inhibits the expression of miR‐214 by binding EZH2 and promotes the progression of ovarian cancer." (PMID 38098223, 2024). "Upregulated ALKBH5 demethylated the long noncoding RNA PVT1 and thus stabilized FOXM1, at least partially, in ovarian cancer." (PMID 38098223, 2024).
ovarian carcinoma (continued). "A recent study showed that blockade of lncRNA PVT1 reduced the expression of PD-L1 through the JAK2/STAT3 pathway, thereby inhibiting cell proliferation and invasion in cisplatin resistant epithelial ovarian cancer." (PMID 37936074, 2023). "To next evaluate if PVT1 levels correlate with a mesenchymal gene signature in ovarian cancer patients we examined a panel of EMT genes and PVT1 in the ovarian cancer TCGA data." (PMID 35820706, 2022). "One study showed that lncRNA PVT1 was elevated in cisplatin resistant ovarian cancer tissues, while lncRNAs TUG1 and MEG3 were decreased in ovarian cancer patients with cisplatin resistance." (PMID 36105363, 2022). "We find a strong correlation between PVT1 and MYC in ovarian cancer, as has been previously documented." (PMID 35820706, 2022). "Here we demonstrate that PVT1 is a contextual oncogenic lncRNA, amplified along with MYC, and a prognostic indicator in ovarian cancers that is dynamically altered in expression primarily in response to cellular stressors." (PMID 35820706, 2022). "To test if PVT1 changes in response to cell density were a feature of mesenchymal cells, we induced EMT in epithelial ovarian cancer OVCAR3 and OVCA420 cells with TGFβ-1." (PMID 35820706, 2022). "In conclusion, circular PVT1 increased FOXM1 level via binding to miR-149-5p and thus affected ovarian cancer cell viability and migration." (PMID 33391456, 2021). "Our data have shown a new pathway circular PVT1 affected ovarian cancer cell viability and metastasis via miR-134-5p/FOXM1, thus providing a hint of uncovering novel countermeasure for ovarian cancer." (PMID 33391456, 2021). "Both si‐PVT1#1 and si‐PVT1#2 transfection in SKOV3 ovarian cancer cells significantly down‐regulated the PVT1 expression." (PMID 34288373, 2021). "In this study, we aimed to determine the PVT1 and AGO1 expression in human ovarian cancer tissues and cell lines." (PMID 34288373, 2021). "In conclusion, circular PVT1 increased FOXM1 level via binding to miR-149-5p and thus affected ovarian cancer cell viability, apoptosis and drug resistance." (PMID 33391456, 2021). "A qualitative evaluation of ovarian cancer revealed the top 20 predictions by LION contained all four experimentally validated lncRNAs: MALAT1, H19, HOTAIR, and PVT1." (PMID 31379598, 2019). "Concurring with these observations, siRNA-mediated silencing of PVT1 resulted in a reduction in MYC protein levels in different tumor types such as colorectal carcinoma, breast, and ovarian cancer." (PMID 31781490, 2019). "While MYC and PVT1 knock-downs both reduced proliferation of breast and ovarian cancer cell lines with amplification and over-expression of MYC and PVT1, knock-down of PVT1 in these lines also elicited a strong apoptotic response." (PMID 19419571, 2009). "Tools to silence lncRNAs are currently available (RNA interference, antisense oligonucleotides and genome editing [CRISPR/Cas9 system]), but none have been clinically used for PVT1 and warrant further investigation for ovarian cancers." (PMID 35820706, 2022). "Additionally, in our study, we only demonstrate the important regulatory effects of PVT1/miR‐148a‐3p/AGO1 axis in SKOV3 cell line, and other ovarian cancer cell lines such as A2780, COC1, OVCAR3 and CAOV3 should also be further investigated." (PMID 34288373, 2021). "All of these studies indicate that miRNA may act as an intermediary bridging PVT1 and AGO1 to regulate the ovarian cancer progression." (PMID 34288373, 2021). "For example, we studied the TGF‐β pathway downstream the PVT1/miR‐148a‐3p/AGO1 signalling; however, there may be other pathways that are also participate in the regulatory roles of this axis on ovarian cancer cells, which are also worth studying." (PMID 34288373, 2021). "Furthermore, we discovered that PVT1 up‐regulated the expression of AGO1 and thus regulated the transforming growth factor‐β (TGF‐β) pathway to promote ovarian cancer progression through sponging miR‐148a‐3p." (PMID 34288373, 2021).
ovarian carcinoma (continued). "Our RNA immunoprecipitation experiment indicated that PVT1 bound histone methyltransferase enhancer of zeste homolog 2 (EZH2), and regulated the expression of target gene, including p57, and consequently altered ovarian cancer cell biology." (PMID 33763107, 2020). "PVT1 is overexpressed, compared to healthy tissues, in breast and ovarian cancer, pediatric malignant astrocytomas, AML and Hodgkin lymphoma, suggesting that PVT1 could be an oncogene." (PMID 23887658, 2013). "In addition, PVT1 was shown to act independently of MYC, when amplified and overexpressed, through increasing cell proliferation and inhibiting apoptosis in breast and ovarian cancer cell lines." (PMID 33670447, 2021). "However, in a subset of ovarian cancer cell lines including OVCAR3 and OVCA420, cell density alterations failed to induce changes in PVT1 expression (data not shown)." (PMID 35820706, 2022).